NUMB (NUMB endocytic adaptor protein)
Diseases named in the same sentence as NUMB in open-access papers (continued):
Sharing a sentence is not in itself a finding about the gene and the disease.
cancer (continued). "According to previous reports, MSI2 can interact with mRNAs and regulate the translation of several oncogenic proteins related to cancer signaling pathways, such as the TGFβ/SMAD, mTOR, PI3K/Akt, cMET, NUMB/Notch, cMyc, and Hh signaling pathways." (PMID 39990676, 2025). "Using in vitro and in vivo studies, we show that RAB4A, as the upstream regulator, relays signal stepwise to NUMB, NOTCH1, RAC1, and then SOX2 to control the self-renewal property of multiple cancer cells of diverse tissue origins." (PMID 39463384, 2024). "So far, we have demonstrated that NUMB, NOTCH1, and RAC1 regulate cancer cell self-renewal downstream of RAB4A, and that this signaling chain controls the transcription of SOX2." (PMID 39463384, 2024). "In conclusion, these studies in both RAB4A-high and RAB4A-low cancer cells demonstrate that RAC1 is upstream of SOX2 in the RAB4A regulation of cancer stemness, while the order of regulation among RAC1, NUMB, and NOTCH1 are yet to be defined." (PMID 39463384, 2024). "We then validated the levels of NUMB, NOTCH, and SOX2 in a number of RAB4A-high cancer cells (MDA-MB-231, PC3, and SNB19) in response to RAB4A knockdown, and in RAB4A-low cancer cells (MCF7 and H1299) in response to RAB4A over-expression." (PMID 39463384, 2024). "Compared to NUMB, less is known about the expression and role of NUMBL in most types of cancer until now." (PMID 37657045, 2023). "A more representative example is its role in tumorigenesis, where NUMB and NOTCH establish a delicate balance that, if disturbed, can lead to aberrant differentiation and cancer progression and metastasis." (PMID 36672267, 2023). "To date, the ultimate mechanisms of NUMB and NUMBL mediating cancer processes concentrate on breast, lung, colon, prostate, liver, and pancreatic cancers." (PMID 37657045, 2023). "Emerging publications have reported functional links between NUMB/NUMBL and clinicopathologic features in many types of cancers." (PMID 37657045, 2023). "Herein, the corresponding heatmap also showed a positive correlation between NUMB or NUMBL and their above targeting genes in the majority of detailed cancers." (PMID 37657045, 2023). "It is differential that the expression status of NUMB and NUMBL across various cancer types of TCGA." (PMID 37657045, 2023). "Here, we have focused on CD44 and NUMB as two ESRP1-specific AS target genes with well-established functional roles in EMT and in cancer invasion and metastasis." (PMID 36346211, 2022). "In summary, our work has provided strong evidence that NUMB isoforms played opposing roles in the regulation of EMT, cancer cell migration and metastasis." (PMID 35457181, 2022). "Taken all together, our study provides mechanistic insights into the opposite regulation of Notch1-SMAD3 crosstalk by NUMB isoforms and identifies them as critical regulators of EMT and cancer cell migration." (PMID 35457181, 2022). "Our data further reveal that NUMB p65/p66 isoforms increase Notch1 activity, and N1ICD works in concert with SMAD3 to promote EMT and thus enhance cancer cell migratory abilities." (PMID 35457181, 2022). "Inclusion of NUMB exon 12 is frequently observed in different types of cancer, leading to a 48 amino acid extension of the proline-rich region (PRR) of the NUMB protein." (PMID 36304260, 2022). "From the newly generated lists of RBP-specific AS targets, we selected CD44 and NUMB for further analysis, based both on their ESRP1-specific AS patterns and on their well-established roles in EMT, stemness/differentiation, and cancer progression." (PMID 36346211, 2022). "Docetaxel activated Notch signaling and suppressed NUMB, which lead to increased survival and EMT acquisition in cancer cells, resulting on enhanced chemoresistance to drugs." (PMID 33968932, 2021). "Further study found that the TDP43/SRSF3/PAR3 axis regulated the metastasis of cancer cells, while the TDP43/SRSF3/NUMB axis controlled the proliferation of cancer cells." (PMID 33072610, 2020).
cancer (continued). "This phenomenon suggests that NUMB and NUMBL act as essential regulators of cancer cell properties, individually acting in a dose-dependent manner and regulating the same pathway with a certain degree of redundancy." (PMID 29507685, 2018). "The distinct role of NUMB in EMT in different physiological process highlights the importance of cell context and genetic background in development and cancer EMT processes." (PMID 27506933, 2016). "Next, we examined the Notch signaling pathway, which is extensively studied as a critical regulator of the cancer EMT program and is negatively regulated by NUMB during asymmetric cell division." (PMID 27506933, 2016). "The AS events significantly altered in all three cancer types include many genes whose splicing was known to play critical roles in cancer development, such as the CD44, NUMB, and FN1." (PMID 25749525, 2015). "Most of the candidate genes of which we confirmed cancer-specific AS in NSCLC are also involved in these processes (ADD3, CLSTN1, FN1, MYO18A, NUMB, SYNE2, and TPM1)." (PMID 21118496, 2010). "In accordance with our results, a pan-cancer analysis systematically investigates the role and function and relevant molecular mechanisms of NUMB and NUMBL in majority types of cancer, and discusses the similarities and divergences between these 2 homologous proteins." (PMID 37657045, 2023). "Consequently, these results furnish novel expectations into the functional roles of NUMB/NUMBL in diversified human malignancies, emphasizing the potential molecular mechanisms of NUMB/NUMBL in the tumorigenicity and clinical prognosis in different cancers." (PMID 37657045, 2023). "This study aimed to investigate the prognostic significance for NUMB and NUMBL in pan-cancer." (PMID 37657045, 2023). "Furthermore, NUMB plays a role in regulating the endocytosis of ALK (anaplastic lymphoma kinase), a receptor that is often aberrantly expressed in cancer." (PMID 36672267, 2023). "In cancer, EMT promotes NUMB exon skipping, supporting acquisition of invasive properties." (PMID 31877720, 2019). "Although KRT19 regulates EGR1/PTEN/AKT, β-catenin/NUMB/NOTCH, and HER2/ERK/SP1 cascades, we focused on the AKT, GSK3β, ERK, Src, and JNK signaling pathway in this study, as these signaling pathways are crucially involved in cancer progression." (PMID 29747452, 2018). "Thus, it is plausible that the NUMB and NUMBL isoforms are essential in terms of their different regulatory effects on the properties of cancer." (PMID 29507685, 2018). "In the present study, we aimed to explore the miR-129 controlling of suppressive Let-7 in regulation of NUMB/NOTCH signaling, which will help to reveal the mechanistic involving of stem cells’ signature, paving the way for prospect strategy of eliminating cancer stem-like cells." (PMID 29262559, 2017). "The NUMB inhibition exerted similar facilitation as Fluorouracil did, however, the enforced miR-129 and NICD inhibition both abolished the oncogenic promotion of Fluorouracil on self-renewing ability of cancer stem-like cells." (PMID 29262559, 2017). "In this article, our main objective was to find out the effects of those cross talking molecules, such as RAS, TWIST, ERK12, NOTCH1 or the loss of functions of few tumor suppressor proteins such as SUFU, GAS1, SUFU, NUMB, SNO in the three types of cancer scenarios discussed earlier." (PMID 23935937, 2013). "Furthermore, epigenetics mutation frequency of NUMBL is higher than NUMB among different cancers, and altered NUMBL, rather than NUMB, associated to lower OS and DFS of UCEC patients." (PMID 37657045, 2023). "In cancer, NUMB is involved in the non-random segregation of subcellular vesicles." (PMID 36672267, 2023). "A similar NUMB splice pattern was observed across other cancer types (data not shown)." (PMID 36304260, 2022).
cancer (continued). "RNA binding protein RBM5/6 and 10 could differentially control alternative splicing of a negative Notch regulator gene NUMB, thus antagonistically regulating the Notch signaling activity for cancer cell proliferation." (PMID 27536874, 2016). "Furthermore, we show that QKI-5 regulates the alternative splicing of NUMB, thereby inhibiting cancer cell proliferation and preventing the activation of the Notch signaling pathway." (PMID 24722255, 2014). "Interestingly, NUMB is also involved in asymmetrical division of stem-like cancer cells, therefore, aberrant AS may also affect the balance between stem-like and non-stem cancer cells." (PMID 31877720, 2019).
infection (2 papers, 2019 to 2021). The state of being infected such as from the introduction of a foreign agent such as serum, vaccine, antigenic substance or organism. "However, the HBcAg-negative area in past infection tissues showed strong ITCH and NUMB accumulation, suggesting that the E3 pathway was negatively correlated with HBV infection and Notch activity." (PMID 30733490, 2019).
cardiovascular disease (1 paper, 2022). "However, to our knowledge, the role of the NUMB gene has not yet been studied in correlation to cardiovascular disease development and progression." (PMID 35529060, 2022).
hematologic malignancies (1 paper, 2012). "Conversely, activation of NOTCH1 signaling through gain-of-function mutations in NOTCH1, first described in T-ALL, or loss-of-function mutations in NOTCH1 regulators, such as FBXW7 and NUMB, has been linked to therapeutic recalcitrance of hematologic malignancies." (PMID 22768113, 2012).
NUMB also shares sentences with these, for which no sentence is quoted: esophageal squamous cell carcinoma (3 papers); Hepatic fibrosis (2); squamous cell carcinoma (2); adenocarcinoma (1); alcoholic cirrhosis (1); B-cells lymphoma (1); brain cancer (1); cervical (1); colon adenocarcinoma (1); esophageal (1); esophageal carcinoma (1); head and neck squamous cell carcinoma (1); Hepatitis (1); hepatitis B (1); hyperuricemia (1); invasive ductal carcinomas of breast (1); lymphoid neoplasm (1); meningioma (1); mesothelioma (1); ovarian serous cystadenocarcinoma (1); prostate adenocarcinoma (1); prostate tumours (1); pulmonary stenosis (1); rectum adenocarcinoma (1); salivary gland carcinoma (1); Salmonella Infections (1); skin cutaneous melanoma (1); stomach adenocarcinoma (1); testicular cancer (1); thymoma (1).
A further 2 diseases each share a sentence with NUMB in 1 paper.